SAA1 (serum amyloid A1)
Diseases named in the same sentence as SAA1 in open-access papers (continued):
Sharing a sentence is not in itself a finding about the gene and the disease.
tumor (continued). "SAA1 is acknowledged for its role as a cytokine-like protein facilitating cell-to-cell communication and feedback in inflammatory, immunological, tumor, and protective pathways." (PMID 41029721, 2025). "SAA1 can also modulate the immune response, potentially leading to tumor evasion and therapy resistance." (PMID 40299483, 2025). "Among them, FLRT3, ATP1A1, and KCNJ15 were expressed at decreased levels in tumor samples, and the expression of SAA1 was increased in tumor samples." (PMID 38358909, 2024). "The PLOD2 + SAA1 + tumor subtype displays intricate intercellular crosstalk and provides insights into the underlying molecular pathogenesis for ccRCC." (PMID 38951896, 2024). "Based on our findings, we observed that PLOD2 + SAA1 + tumor cells were able to communicate with TME cells and act as strong senders and influencers in signaling pathways such as SPP1, MIF, PTN, and MK." (PMID 38951896, 2024). "We constructed a subcutaneous xenograft tumor model in nude mice to investigate the role of SAA1 in vivo." (PMID 38446289, 2024). "Our secretome analysis uncovered SAA1 as a major factor of the SASP of palbociclib-induced senescent tumor cells." (PMID 38693312, 2024). "The results showed that the tumor volume and tumor weight in the SAA1-overexpression group were larger than those in the OE-NC group." (PMID 38446289, 2024). "We observed that the percentage of PLOD2 + SAA1 + tumor cells with high MECRGS scores, as well as the expression of immune checkpoints such as NECTIN2 and CD47, increased in patients who exhibited a partial response (PR) to immunotherapy." (PMID 38951896, 2024). "Regarding the surrounding normal hepatocytes, a recent paper identified an invasive zone around the iCCA tumor border containing a subpopulation of damaged hepatocytes with increased serum amyloid A1 (SAA1) and A2 (SAA2) expression." (PMID 39256888, 2024). "The results showed that, regions of high SAA1 expression highly overlapped with regions of cell adhesion molecules pathway hyperactivity in the tumor cell cluster." (PMID 38658579, 2024). "Our findings indicate that SAA1 modulates the migration ability of tumor cells via the ERK-AP1-MMPs axis." (PMID 38658579, 2024). "In contrast, compared to normal tissues, tumor tissues showed noticeably elevated expression levels of SAA1, MDK, and ISG15." (PMID 39440053, 2024). "Within the 250 μm wide region adjacent to the tumour border, the damaged area induces high expression of SAA1 and SAA2 by CXCL6." (PMID 39350478, 2024). "Next, we investigated PLOD2 + SAA1 + tumor cells’ interactions with other types of cells in the TME." (PMID 38951896, 2024). "The unchanged levels of cell cycle markers in this study, in contrast to the decreased proliferation markers observed in the CAC model, highlight the potential context-dependent role of SAA1/2 in tumor biology." (PMID 39336082, 2024). "Western blotting results of paired samples from 10 pairs of ccRCC patients similarly demonstrated that SAA1 is highly expressed in tumor tissue." (PMID 38658579, 2024). "SAA1 is largely regarded as a protumorigenic factor and contributes to tumor initiation and progression via the MAPK/ERK, Akt, NF-κB and IL-1 pathways." (PMID 38446289, 2024). "For all included clinical features (age, grade, T stage, N stage, M stage, TNM stage, tumor size), PD-L1, and SAA1 were powerful and risky (HR > 1) prognostic indicators in our dataset." (PMID 37108666, 2023). "Meanwhile, the expression level of hub genes BDKRB1, NMUR2, PMCH, and SAA1 in pRCC tissues was significantly positively correlated with tumor stage, lymph node metastasis, and the histopathology grade of pRCC." (PMID 36785669, 2023). "In order to further validate the role of SAA1 in the development and progression of ccRCC, clinical ccRCC tumor samples and adjacent normal tissues were collected for IHC staining analysis." (PMID 37108666, 2023).
tumor (continued). "Within the zone, intense suppression of the local immune microenvironment, metabolic reprogramming of tumor cells, and severely damaged hepatocytes with high expression of serum amyloid A1 and A2 (SAA1, SAA2, referred to collectively as SAAs) were noted." (PMID 37337030, 2023). "The ROC curves indicated that, when SAA1 was combined with important clinicopathologic features including age, T stage, N stage, M stage, grade, and tumor size, the combination model achieved a better performance than when alone, respectively." (PMID 37108666, 2023). "A paired analysis of the SAA1 expression in normal tissue and tumor tissue of the same patients revealed similar results." (PMID 37108666, 2023). "The expression of SAA1 was significantly higher in the ccRCC tumor tissues with advanced samples compared with early stage or normal samples." (PMID 37108666, 2023). "SAA1 knockdown in ccRCC cells inhibits tumor migration and invasion, and high SAA1 expression predicts poor prognosis." (PMID 36330441, 2022). "In vitro wound healing and transwell assays confirmed a strong invasion capacity of ESCC tumor cells with high expression of SAA1." (PMID 36605443, 2022). "For example, a large number of studies have reported that SAA1 promotes tumor progression and accelerates distant metastasis." (PMID 34084746, 2021). "In a sample of 233 different tumor patients, higher SAA1 levels appeared in more advanced tumor patients." (PMID 34084746, 2021). "Significant overexpression of SAA1 has been observed in various types of cancer and directly correlates with poor prognosis and tumor progression." (PMID 32921632, 2020). "As expected, we observed an increase in the levels of markers that are important for immune responses and inflammation (Saa1, Saa2, Lcn-2, Ltf, and Orosomucoid-2) and initiating and promoting tumor growth (Ighg1, Scube3, and Fgl1)." (PMID 33110211, 2020). "For this purpose, they injected an AAV–miRNA targeting SAA1/2 or an AAV–control–miRNA into C26 tumour‐bearing mice." (PMID 32049447, 2020). "Recently, it has been reported that SAA1 the expression levels in GBM patients are upregulated on both mRNA and protein in human GBMs, and SAA1 involves in angiogenesis via HIF-1α and tumor associated macrophages." (PMID 30867991, 2019). "Based on the intersection of APP signature between human BC tissues and cell lines to exclude the tumor heterogeneity, SAA1 and SAA2 were highly expressed both TNBC tissues and cell lines." (PMID 30728901, 2019). "In a BC mouse model, ectopic expression of SAA1 or SAA3 in tumor cells potently promoted widespread metastasis." (PMID 30728901, 2019). "We also detected the SAA1 distribution in a GBM mouse model; enriched SAA1 was found around the tumor infiltration region (D1, and D2)." (PMID 29603594, 2018). "Magnetic resonance imaging and tumor region‐specific microarray analysis identified a correlation between SAA1 and GBM cell infiltration in patients." (PMID 29603594, 2018). "Results from both MRI and tumor region‐specific microarray assessments further validated the distribution and effect of SAA1 in GBM infiltration." (PMID 29603594, 2018). "To investigate the role of SAA1 in GBM tumor progression, we tested the effects of both intracellular SAA1 and extracellular SAA1 on cell migration and invasion by using a transwell assay." (PMID 29603594, 2018). "Plasma SAA1 level is a known biomarker for tumour malignancy, host response, and chemotherapy resistance." (PMID 25652121, 2015). "This balance and crosstalk underscores the importance of type I NKT cells in the regulation of tumor immunity and introduces an opportunity to exploit NKT agonists in tumor settings where inflammatory proteins like SAA-1 are released." (PMID 25389427, 2014). "SAA1, a high-density lipoprotein (HDL)-associated apolipoprotein, is an acute-phase protein which is elevated in response to trauma, inflammation, and neoplasia." (PMID 22040021, 2011).
tumor (continued). "Studies have shown that SAA1 may play a role in cancer development, tumor evasion, resistance to therapy and progression by promoting metastasis." (PMID 40299483, 2025). "In vivo, SAA1 promoted tumor progression and ascites formation." (PMID 41029721, 2025). "One such reported case is colorectal cancer invasion that could be affected by tumor-derived IL-1β, which induces the expression of human SAA1." (PMID 39940756, 2025). "SAA1 is a secreted protein that is produced in an inflammatory response when tissue damage occurs and is involved in the regulation of the immune response, tissue repair and tumor progression." (PMID 40299483, 2025). "Upon dissection, fewer tumor nodules were observed on the abdominal wall in the SAA1-KO group." (PMID 41029721, 2025). "Besides, anti-PD-1 immunotherapy significantly shrunk the primary tumor and reduced lung metastasis in Saa1 ablation (Saa1−/−) mice that were orthotopically implanted with hepa-luci+ cells in the liver." (PMID 38409200, 2024). "The significant interaction between species and time observed in tumor growth suggests that the role of SAA1/2 may be more complex and could vary during different stages of tumor development." (PMID 39336082, 2024). "Through mIF and IHC techniques applied to the Renji TMA cohort, we were able to identify the presence of PLOD2 + SAA1 + ccRCC cells and we found this tumor subclusters were related with high infiltration of CD163 + macrophages and Treg cells, indicating the establishment of an immunosuppressed TME." (PMID 38951896, 2024). "In addition, HCCs with high expression of SAA1 exhibited higher immune score, stromal score, and Estimate score, indicating abundant immune infiltration and lower tumor purity." (PMID 38627760, 2024). "However, we also noted an increase in the expression of certain tumor related genes, including SAA1, KRT19 and NUPR1." (PMID 38951896, 2024). "The PLOD2 + SAA1 + tumor cells could communicate with other cells through ligand-receptor pairs like SPP1-CD44, MIF-(CD74 + CXCR4), and MDK-LRP1." (PMID 38951896, 2024). "This contrasts with our previous findings in a colitis-associated cancer (CAC) model, where the absence of SAA1/2 led to a significant reduction in tumor formation and a less proliferative tumor phenotype in SAADKO mice." (PMID 39336082, 2024). "This discrepancy underscores the need for further investigation into the specific mechanisms by which SAA1/2 may influence tumor biology across different cancer types." (PMID 39336082, 2024). "The up-regulated genes included serum amyloid A1 (SAA1), a known tumor biomarker." (PMID 38541076, 2024). "Previous literatures have reported that SAA1 could contribute to cancer development and accelerate tumor progression and distant metastasis." (PMID 37081987, 2023). "The upregulation of SAA1/2 could increase the invasive potential of tumor cells in RCC and lead to massive T-cell infiltration, which might explain the sex bias of malignant cells and T-cells infiltration." (PMID 37715192, 2023). "We also found that male tumors had a significantly higher SAA1 expression than the tumor females." (PMID 37715192, 2023). "To validate the relationship between the SAA1 expression, mast cells resting proportion, and tumor grade or stage, we verified the SAA1 expression and mast cells resting proportion in the GEO datasets by different tumor grades or tumor stages." (PMID 37108666, 2023). "The overexpression of SAA1 induced tumor proliferation and migration by regulating the Akt pathway, which might determine the clinical outcome of patients with ccRCC." (PMID 37108666, 2023). "In addition, a large number of studies have reported that SAA1 promotes tumor progression and accelerates distant metastasis." (PMID 37081987, 2023).
tumor (continued). "Additionally, the tumor suppressive genes SAA1, VSIR, and BCL3 were also significantly upregulated in ACM samples." (PMID 36428692, 2022). "A tumor-bearing SAA1/2 knockout mouse model was also utilized in this study." (PMID 36248994, 2022). "Moreover, CD204 suppresses tumor development through the upregulation of serum amyloid A1 (SAA1) expression in TAMs via JNK/ERK/IκB/NFκB signaling pathways." (PMID 36686729, 2022). "Additionally, tumor suppressive genes SAA1, VSIR, and BCL3 were also significantly upregulated in ACM samples." (PMID 36428692, 2022). "CIBERSORT analysis of the tumor-infiltrating immune cell proportion revealed that M2 macrophages, neutrophils, activated mast cells, resting mast cells, and regulatory T cells were correlated with SAA1 expression." (PMID 35756918, 2022). "Moreover, with the increase of tumor stage and grade, the degree of SAA1 gene methylation decreased accordingly, which means that the degree of SAA1 gene methylation was inversely related to the tumor’s stage." (PMID 34084746, 2021). "Extensive literatures have reported that SAA1 could contribute to cancer development and accelerate tumor progression and distant metastasis." (PMID 34084746, 2021). "The inclusion of SAA1 in a panel of markers distinguishing adenocarcinoma from SqCC patients is explained not only by histological, cellular, and molecular factors, but also by tumor localization in the lungs." (PMID 34439874, 2021). "In addition, the role of SAA1 in tumor progression and its potential as a biomarker have also been extensively studied." (PMID 34084746, 2021). "Since there is a correlation between chronic inflammation and malignant transformation, studies suggest that SAA1 may affect oncogenesis and tumor metastasis." (PMID 34884984, 2021). "In addition, a large number of studies have confirmed the positive correlation between SAA1 concentrations and tumor stage." (PMID 34084746, 2021). "SAA1 expression in tumor tissues is upregulated at mRNA levels." (PMID 34084746, 2021). "Specifically, we note the large induction of SAA1/2 in the plasma of tumor bearing mice." (PMID 33063952, 2020). "Collectively, these results suggest that tumor-derived SAA1 may act via TLR4 receptor to induce the activation of p38 and JNK signaling to disrupt cell–cell junctions of lymphatic vessels, promoting lymphatic invasion." (PMID 31390756, 2019). "Given the observation that SAA1 can be shed by tumor cells and reach the plasma, SAA1 may recruit peripheral immune cells such as macrophages and monocytes into the tumor microenvironments." (PMID 29603594, 2018). "In this study, we used both H1415 and K9218 monoclonal antibodies to detect P1/P2- and P1-promoter-driven HNF4α, respectively, in the liver and tumor samples to determine how the expression of these two isoforms may play a role in SAA1 expression patterns." (PMID 28938650, 2017). "Because this effect was proportional to the numbers of type I NKT cells added in vitro, it would be interesting to see if greater quantities of NKT cells in vivo would shift the equilibrium in immune reaction to SAA-1 further, decreasing IL-10 mediated suppression, and restoring tumor immunity." (PMID 25389427, 2014). "Among them, in particular, serum amyloid A proteins, SAA1 and SAA2, secreted by cancer cells, cancer-associated fibroblasts, tumor-associated macrophages and adipose cells in the tumor microenvironment, may promote cancer cell proliferation, metastasis and survival." (PMID 41387465, 2025).
tumor (continued). "Furthermore, the analysis to evaluate the relationship with SAA1 and clinical characteristics was conducted, and the Wilcoxon rank sum test showed that the expression of SAA1 was significantly upregulated in the tumor samples compared with the normal samples." (PMID 37108666, 2023). "Furthermore, we performed ESTIMATE and CIBERSORT analysis and the results revealed that SAA1 might be an indicator for immune infiltration of the tumor microenvironment in ccRCC patients." (PMID 37108666, 2023). "In order to verify whether SAA1 is a potential prognostic factor in ccRCC patients, we compared the prognostication performance of the traditional clinicopathologic features (including age, T stage, N stage, M stage, grade, tumor size, and immune therapy molecular PD-L1) and our biomarker SAA1." (PMID 37108666, 2023). "Furthermore, GO and KEGG enrichment analysis suggested that SAA1 may involve in tumor-related pathways and co-expressed with tumor metastasis-related proteins." (PMID 37081987, 2023). "Notably, the tumor cells were observed to be close to SAA1/2, SAA3, citrullination, and Fbg." (PMID 37620307, 2023). "However, the diagnostic and prognostic potential of SAA1 at the tumor tissue level and its biological function in ccRCC have not been reported." (PMID 34084746, 2021). "In addition, SAA1 could serve as a biomarker for the diagnosis and prognosis of advanced and metastatic renal cell carcinoma at the tumor tissue level." (PMID 34084746, 2021). "In addition, among a total of nine patients whose plasma and tissue SAA1 levels could be compared, plasma SAA1 levels were positively correlated with tumor SAA1 labeling." (PMID 29603594, 2018). "Additionally, we found a specific distribution of SAA1 in tumor microenvironments." (PMID 29603594, 2018). "10.13039/100014337Furthermore, RT-qPCR analysis showed a significant decrease in the mRNA expression of MTOR, CD44, and SAA1 in the combination group, further supporting the synergistic effect of PF-309 and OXA in inhibiting tumor growth." (PMID 41459112, 2026). "Although research on SAA1 in NPC is limited, key findings suggest its potential role in tumor progression." (PMID 40565234, 2025). "Compared with normal tissues, the top three downregulated genes in the tumor tissues were FABP4, SAA1, and SFRP1, while the top three upregulated genes were COMP, COL10A1, and MMP11." (PMID 40936892, 2025). "To examine MDSC-tumor interactions, we analyzed the GSE145374 dataset, identifying CSF2, SAA2, IL6, SAA1, and BCL2A1 as the top five upregulated differentially expressed genes in SKOV3 cells after co-culture with MDSCs." (PMID 41029721, 2025). "A decreased abundance of SAA1 in HCC, correlated with reduced survival rates and involvement in anti-tumor immune pathways, was observed." (PMID 39286634, 2024). "The bulk RNA-seq data from validation cohort 2 also revealed higher SAA1 and SAA2 expression levels around the border areas (bilateral sampling of 5 mm-wide tissues along the border) than in the corresponding tumor and paratumor tissues (n = 10)." (PMID 37337030, 2023). "It was recently reported that S100A4 enhanced the expression of mouse SAA1 and SAA3, which stimulated expression of RANTES, G-CSF, MMP2, S100A8, and S100A9 to promote tumor metastasis." (PMID 35936690, 2022). "Examples of genes with more expression per cell in the erlotinib-treated group are PLAAT3, LCN2, CEBPD, and SAA1; conversely, LDHB is shown as an example for transcripts more abundant in control tumor cells." (PMID 36482068, 2022). "The slowest tumor growth rate was observed when a combination of anti-LY6G and anti-SAA1 mAbs were used together." (PMID 36555469, 2022).